TMPRSS2 (transmembrane serine protease 2)
Description:
Plasma membrane-anchored serine protease that cleaves at arginine residues. Participates in proteolytic cascades of relevance for the normal physiologic function of the prostate. Androgen-induced TMPRSS2 activates several substrates that include pro-hepatocyte growth factor/HGF, the protease activated receptor-2/F2RL1 or matriptase/ST14 leading to extracellular matrix disruption and metastasis of prostate cancer cells. In addition, activates trigeminal neurons and contribute to both spontaneous pain and mechanical allodynia (By similarity). (Microbial infection) Facilitates human coronaviruses SARS-CoV and SARS-CoV-2 infections via two independent mechanisms, proteolytic cleavage of ACE2 receptor which promotes viral uptake, and cleavage of coronavirus spike glycoproteins which activates the glycoprotein for host cell entry. The cleavage of SARS-COV2 spike glycoprotein occurs between the S2 and S2' site. Upon SARS-CoV-2 infection, increases syncytia formation by accelerating the fusion process. Proteolytically cleaves and activates the spike glycoproteins of human coronavirus 229E (HCoV-229E) and human coronavirus EMC (HCoV-EMC) and the fusion glycoproteins F0 of Sendai virus (SeV), human metapneumovirus (HMPV), human parainfluenza 1, 2, 3, 4a and 4b viruses (HPIV). Essential for spread and pathogenesis of influenza A virus (strains H1N1, H3N2 and H7N9); involved in proteolytic cleavage and activation of hemagglutinin (HA) protein which is essential for viral infectivity. (Microbial infection) Receptor for human coronavirus HKU1-CoV, acts synergistically with disialoside glycans to facilitate the entry of the virus. After binding to cell-surface disialoside glycans, the viral S protein interacts with the inactive form of TMPRSS2 and inhibits its protease activity.
Synonyms: PRSS10; LOC124905021
Tractability: Small molecule: a structure with a bound ligand is known; a high-quality ligand is known. Antibody: UniProt places it where antibodies can reach, with high confidence; its Gene Ontology location is reachable by antibodies, with high confidence; UniProt predicts a signal peptide or a membrane-spanning region; the Human Protein Atlas places it where antibodies can reach. PROTAC: its protein half-life has been measured; a small molecule that binds it is known.
Target class: Enzyme; Protease; Serine protease
Gene: Protein-coding gene on chromosome 21 (41,464,296 to 41,531,116, reverse strand). Ensembl gene ENSG00000184012.
Subcellular location: Cell membrane; Secreted (Transmembrane protease serine 2 catalytic chain)
Subcellular location (Human Protein Atlas): Plasma membrane; Predicted to be secreted
Pathways (Reactome):
Disease: Attachment and Entry; Induction of Cell-Cell Fusion
Gene Ontology:
Molecular function: protein binding; serine-type endopeptidase activity; serine-type peptidase activity
Biological process: entry receptor-mediated virion attachment to host cell; positive regulation of viral entry into host cell; protein autoprocessing; proteolysis
Cellular component: extracellular exosome; plasma membrane; extracellular region; membrane
Genetic constraint (gnomAD): Loss-of-function variants: 55 observed, 69.45 expected, observed/expected ratio (o/e) 0.79, 90% interval 0.64 to 0.99. The upper end of that interval is the gene's LOEUF score, 0.99, which puts it in group 4 of 6, group 1 being the genes least tolerant of losing a copy. Missense variants: 664 observed, 662.31 expected, observed/expected ratio (o/e) 1, 90% interval 0.94 to 1.07. Synonymous variants: 256 observed, 263.53 expected, observed/expected ratio (o/e) 0.97, 90% interval 0.88 to 1.08.
Homologues: Orthologues: chimpanzee TMPRSS2 (98% identical), macaque TMPRSS2 (87% identical), dog TMPRSS2 (80% identical), mouse Tmprss2 (78% identical), rat Tmprss2 (78% identical), pig TMPRSS2 (77% identical), rabbit TMPRSS2 (69% identical), tropical clawed frog tmprss2 (48% identical), tropical clawed frog tmprss2.12 (44% identical), tropical clawed frog tmprss2.2 (43% identical), tropical clawed frog tmprss2.6 (42% identical), tropical clawed frog tmprss2.13 (41% identical), and 4 more. Paralogues in human: TMPRSS3 (35% identical), ST14 (29% identical), TMPRSS13 (28% identical), TMPRSS15 (28% identical), TMPRSS6 (28% identical), TMPRSS7 (26% identical), TMPRSS11D (26% identical), HPN (25% identical), TMPRSS11F (25% identical), TMPRSS9 (24% identical), TMPRSS11E (24% identical), TMPRSS5 (24% identical), and 5 more.
Diseases named in the same sentence as TMPRSS2 in open-access papers:
TMPRSS2 is named in the same sentence as 293 diseases in open-access papers, as found by Europe PMC text mining. Sharing a sentence is not in itself a finding about the gene and the disease. The quoted sentences say what the papers report.
COVID-19 (774 papers, 2020 to 2026). A disease caused by infection with severe acute respiratory syndrome coronavirus 2. "Our result suggesting that the combination of rs4646994 of the ACE gene and rs75603675 of the TMPRSS2 gene is associated with increased risk of severe COVID-19." (PMID 41734172, 2026). "There is a potential association between a TMPRSS2 gene single-nucleotide polymorphism (SNP) causing a V160M mutation and severe COVID-19 disease progression." (PMID 39858469, 2025). "Thyroid hormone levels play a role in coagulation, which is one of the leading causes of death associated with COVID-19; antithrombin, a coagulation regulator, inhibits TMPRSS2, thereby reducing the likelihood of coronavirus infection." (PMID 40296872, 2025). "Given ACE2 and TMPRSS2 polymorphism associations with severe COVID-19, the study will investigate associations with post-COVID symptoms including fatigue and dyspnea." (PMID 40692561, 2025). "Which enzymes beyond transmembrane serine protease 2 are important in humans in vivo for susceptibility to COVID-19?" (PMID 40631549, 2025). "Clinical investigations have found a link between TMPRSS2 expression levels and COVID-19 results, implying that TMPRSS2 polymorphisms can alter the propensity to diseases and their severity." (PMID 40297833, 2025). "Collectively, these observations underscore the need for stratified analyses and functional studies to clarify how ancestry-specific genetic architecture and hormonal milieu shape the phenotypic effects of TMPRSS2 variants in COVID-19." (PMID 40543387, 2025). "Further research identified the rs2070788 GG genetic mutation, which leads to a higher TMPRSS2 protein expression in lung tissue, as correlated with a significant increase in mortality risk among elderly COVID-19 patients." (PMID 39858469, 2025). "Reduced expression of TMPRSS2 has been linked to poorer outcomes in lung cancer and COVID-19 patients, indicating its dual relevance as a target for therapy and prognosis marker." (PMID 40297833, 2025). "TMPRSS2 expression varies widely between populations, which influences COVID-19 susceptibility and severity." (PMID 40297833, 2025). "The association between TMPRSS2 alleles and COVID-19 severity is indeed a topic of discussion in the scientific community." (PMID 39858469, 2025). "In conclusion, genetic studies and meta-analyses have identified a compelling association between TMPRSS2 variants and COVID-19 severity, although further research is needed to elucidate population-specific effects and the underlying biological mechanisms." (PMID 40543387, 2025). "The frequency of the C-allele of the TMPRSS2 gene (rs12329760) in the homozygous state was higher among patients with moderate–severe COVID-19 than in the control group with a mild COVID-19 course by almost 18.06% (χ2 = 3.76; p = 0.05)." (PMID 40573382, 2025). "We conducted a prospective study to compare the expression of ACE2 and TMPRSS2 in the nasal and paranasal sinus tissues among patients with COVID-19-associated mucormycosis, COVID-19-negative mucormycosis (CNM), and healthy individuals." (PMID 39850229, 2025). "A substantial difference in the distribution of TMPRSS2 genotypes was observed between mild and severe COVID-19 cases, with the C allele being more prevalent in severe cases (91.7%) compared to mild cases (22.2%)." (PMID 39858469, 2025). "Research on the TMPRSS2 gene has revealed complex and sometimes conflicting associations with COVID-19 severity." (PMID 40543387, 2025). "This is the first reported case suggesting a potential association between COVID-19-related prostatitis, TMPRSS2::ERG fusion, and prostate cancer development in the absence of hereditary predisposition." (PMID 41267989, 2025). "The aim of this study was to characterize the expression of the two main SARS-CoV-2 entry factors, ACE2 and TMPRSS2, in human hair follicles (HFs) and keratinocytes, thereby providing a molecular basis for the proposed link between COVID-19 and hair loss." (PMID 41298780, 2025).
COVID-19 (continued). "In Brazil, a genetic study involving over 400 hospitalized COVID-19 patients provided additional insights into the influence of TMPRSS2 variants on disease severity and mortality." (PMID 40543387, 2025). "We aim to compare the expression of ACE2 and TMPRSS2 in the nasal and paranasal sinus tissues among patients with COVID-19-associated Mucormycosis (CAM), COVID-19-negative mucormycosis (CNM), and healthy individuals." (PMID 39850229, 2025). "There is supporting evidence indicating the crucial involvement of ACE2 and TMPRSS2 gene variants in determining COVID-19 susceptibility within Indian populations." (PMID 38570613, 2024). "This study measured concentrations of aromatase enzyme, testosterone, estradiol, and TMPRSS-2 in plasma of hospitalized COVID-19 patients to elucidate the dynamics of sex-linked disparity in COVID-19 and correlate them with disease severity and mortality." (PMID 39449074, 2024). "Our study explored the association of TMPRSS2 genetic variants with COVID-19 severity; interestingly, we observed that rs75603675 increased the risk of death due to COVID-19." (PMID 38601158, 2024). "As previous studies reported, another five SNPs at the TMPRSS2/MX1 locus were correlated with a reduced risk of developing severe COVID-19 with the high level of MX1 expression in blood." (PMID 38429664, 2024). "Bioinformatics methods applied to large public domain datasets identified the rs12329760 in TMPRSS2 as a functionally significant variant in COVID-19." (PMID 38263160, 2024). "The Single nucleotide variants (SNVs) in angiotensin-converting enzyme-2 (ACE2) and transmembrane serine protease type-2 (TMPRSS2) genes affect the virus entry and are considered possible risk factors for COVID-19." (PMID 38855114, 2024). "When we used these hormone levels to predict death in hospitalized COVID-19 patients, higher levels of TMPRSS-2 and aromatase were linked to a lower chance of survival." (PMID 39449074, 2024). "In summary, ACE2 and TMPRSS2 expression levels are potential risk factors for the development of symptomatic COVID-19, and the presence of SARS-CoV-2 potentially modulates those levels." (PMID 38606293, 2024). "Our research highlights the potential of genetic markers associated with ACE2 and TMPRSS2 in predicting the severity and outcome of COVID-19, especially in females." (PMID 39744525, 2024). "The association of ACE2 and TMPRSS2 SNVs with COVID-19 infection was performed among the COVID-19 patients and healthy controls." (PMID 38855114, 2024). "From a genetic perspective, certain SNVs in protease genes like TMPRSS2 have been linked to COVID-19 susceptibility or severity." (PMID 38226800, 2024). "A meta-analysis revealed a significant correlation between TMPRSS2 rs12329760 C-allele and an elevated risk of developing severe COVID-19." (PMID 38846354, 2024). "Previous studies have shown that the role of ACE2 and TMPRSS2 gene variants in understanding COVID-19 susceptibility among Indian populations." (PMID 38570613, 2024). "Numerous TMPRSS2 gene variants, particularly COVID-19, have been shown to impact the severity of viral infections." (PMID 38254046, 2024). "Close to our findings of association of this variant with the COVID-19 infection in men, their study concluded that rs17854725 A > G (AA vs. AG and AA vs. GG), among a few other SNVs of TMPRSS2 variations, is associated with severe COVID-19." (PMID 38855114, 2024). "In this study, we aimed to investigate the potential correlation between genetic variants related to viral entry (ACE2 and TMPRSS2) and the presence of circulating cytokines in COVID-19 patients within the United Arab Emirates (UAE) population." (PMID 38855114, 2024). "This study aimed to examine the association between transmembrane serine protease type 2 (TMPRSS2) rs2070788 single nucleotide polymorphism (SNP) and the prognosis of COVID-19 in Iranian populations." (PMID 39188881, 2024).
COVID-19 (continued). "Enzalutamide, a non-steroidal select antagonist of the androgen receptor, has been implicated in the reduction of TMPRSS2 levels in lung cells and its role in COVID-19 treatment has been tested in a double-blinded, randomized phase II clinical trial." (PMID 38254788, 2024). "In conclusion, this case-control study examined the association between the TMPRSS2 rs2070788 SNP and COVID-19 severity in multiple cities across Iran." (PMID 39188881, 2024). "This work was performed to evaluate the possible association between the ACE2 (rs2285666) and TMPRSS2 (rs2070788) SNPs and clinical severity and outcomes among COVID-19 patients." (PMID 39228902, 2024). "Association TMPRSS2 genotypes/alleles distribution with susceptibility to COVID-19, adjusted by age, sex, cigarette smoking, DM, HTN, CVD, and RD." (PMID 39188881, 2024). "Association of TMPRSS2 genotypes distribution with COVID-19 mortality, adjusted by age, sex, cigarette smoking, DM, HTN, CVD, and RD." (PMID 39188881, 2024). "To meet these expectations, we evaluated the association of polymorphisms of ACE2 and TMPRSS2 genes with the likelihood of severe COVID-19 and fatal outcome, separately in females and males." (PMID 39744525, 2024). "Association of TMPRSS2 genotypes/alleles distribution with susceptibility to COVID-19, adjusted by age, sex, cigarette smoking, diabetes mellitus, HTN, CVD, and RD." (PMID 39188881, 2024). "Recent studies have explained the possible role of structural and regulatory variants of TMPRSS2 in susceptibility to COVID-19." (PMID 38601158, 2024). "Having in mind the difference between sexes in terms of COVID-19 susceptibility and outcome, the possible role of TMPRSS2 genotype in this disease is further supported by its androgen-dependent regulation." (PMID 39744525, 2024). "According to the main inherent genetics models of TMPRSS2 rs75603675, a statistically significant association was found between the AA genotype and decreased COVID-19 incidence (OR=1.97; 95% CI 1.07-3.6; P=0.03)." (PMID 38601158, 2024). "In response to these findings, we initiated the first Iranian study to investigate the possible correlation between the TMPRSS2 rs2070788 polymorphism and COVID-19 outcomes, with a particular focus on inflammatory markers." (PMID 39188881, 2024). "In contrast, in TMPRSS2 rs12329760 minor T allele and CT, TT genotypes were significantly associated with a reduced likelihood of developing severe COVID-19." (PMID 38263160, 2024). "Another systematic review and meta-analysis revealed that genetic variants within the angiotensin-converting enzyme 1 and 2 genes (ACE and ACE2, respectively) and the transmembrane serine protease 2 (TMPRSS2) gene were associated with COVID-19 severity." (PMID 38113267, 2023). "Analysis of TMPRSS2 genotypes association with COVID-19 disease severity under five different inheritance models adjusted by gender and age." (PMID 36795725, 2023). "Variants within ACE2 and TMPRSS2 have been extensively studied regarding COVID-19 severity and susceptibility." (PMID 37761938, 2023). "Because ACE2 and TMPRSS2 variants and expression can be candidates for gender and country differences in COVID-19 severity, host genetics is also important in COVID-19." (PMID 37240091, 2023). "It has been shown that some variants of the TMPRSS2 gene can affect the severity of viral diseases such as influenza and COVID-19." (PMID 36795725, 2023). "Several studies have investigated the TMPRSS2 variant (rs12329760) and COVID-19 severity across different Asian and European groups." (PMID 37761938, 2023). "Since AAT and enoxaparin individually and synergistically antagonize several of the pathogenic mechanisms of COVID-19, we posit that they will be more effective than agents that only inhibit TMPRSS2 such as camostat." (PMID 37294003, 2023).